RNU6-196P (RNA, U6 small nuclear 196, pseudogene)
Gene: Small nuclear RNA gene on chromosome 16 (21,642,294 to 21,642,400, forward strand). Ensembl gene ENSG00000207042.
Homologues: Orthologues: chimpanzee U6 (100% identical), macaque U6 (93% identical), pig U6 (86% identical). Paralogues in human: RNU6-211P (93% identical), RNU6-1152P (91% identical), RNU6-116P (91% identical), RNU6-20P (91% identical), RNU6-310P (91% identical), RNU6-35P (91% identical), RNU6-1145P (90% identical), RNU6-1316P (90% identical), RNU6-16P (90% identical), RNU6-25P (90% identical), RNU6-393P (90% identical), RNU6-41P (90% identical), and 1282 more.